CD27 (CD27 molecule)
Diseases named in the same sentence as CD27 in open-access papers (continued):
Sharing a sentence is not in itself a finding about the gene and the disease.
ischemic stroke (2 papers, 2024 to 2025). A stroke disorder caused by obstruction of blood flow to the brain, due to thrombotic (local blood clot formation) or embolic (due to a blood clot or other material traveling from another site) event. "Conversely, increased levels of B cells (CD27 on IgD– CD38br and CD27 on IgD+ CD38– unswitched memory), CD4 on CD39+ CD4+ (Treg), and DN (CD4–CD8–) AC (TBNK) were linked to higher ischemic stroke risk, indicating hazardous effects." (PMID 40620597, 2025).
Listeria infection (2 papers, 2012 to 2018). "Th17 cells reportedly survive poorly after Listeria infection due to their inability to maintain CD27 expression." (PMID 22829762, 2012). "Other studies have shown that CD8+ CD27-, similar to the TemLate phenotype, can protect mice from Listeria infection, though it is not clear if these are primarily Teff or Tmem." (PMID 29630679, 2018).
liver cancer (2 papers, 2024 to 2025). An epithelial or non-epithelial malignant neoplasm that arises from the liver. "Which showed that CD27 expression was significantly reduced in human liver cancer cell line (HUH-7, HepG2, and SMMC-7721) compared to human normal liver cells line (L-O2)." (PMID 38169519, 2024).
Lyme disease (2 papers, 2018 to 2019). Lyme disease (named after the towns in the USA where the disease was first identified) is a bacterial infection caused by Borrelia burgdorferi. "Here, we show that blood plasmablasts and CD27− memory B cells are elevated in untreated Lyme disease, with higher plasmablast levels associated with more rapid resolution of clinical symptoms." (PMID 30072990, 2018). "Interestingly, the proportion of IgD+CD27-naive B cells was not elevated in patients with Lyme disease, reactive arthritis, or septic arthritis." (PMID 30811404, 2019).
lymph node metastasis (2 papers, 2021 to 2022). "In addition, FOS and FOSB were downregulated when lymph node metastasis was present, while CD27 and SELL were upregulated." (PMID 35037412, 2022). "Interestingly, lymph node metastasis was associated with the overexpression of various checkpoints, including PD-L2, TIGIT, TIM-3, ICOS, PD-L1, and CD27." (PMID 33414407, 2021).
lymphoproliferative disorders (2 papers, 2016 to 2017). "Humans deficient in CD27 or CD70 are at risk of lymphoproliferative disorders associated with Epstein-Barr virus (EBV) as a result of reduced proliferation of EBV-specific T cells." (PMID 29198913, 2017).
meningitis (2 papers, 2020 to 2023). A disorder characterized by acute inflammation of the meninges of the brain and/or spinal cord. "Among our subjects with cryptococcal and other forms of meningitis, PD-1 expression was increased on activated B cells, particularly CD27+ and tissue-like memory cells, as reported by others." (PMID 31871098, 2020).
myasthenia gravis (2 papers, 2023 to 2025). Myasthenia gravis (MG) is a rare, clinically heterogeneous, autoimmune disorder of the neuromuscular junction characterized by fatigable weakness of voluntary muscles. "Increased CD27/CD70 signaling has also been reported in myasthenia gravis (MG) patients." (PMID 40211396, 2025).
pertussis (2 papers, 2024). A contagious bacterial respiratory infection caused by Bordetella pertussis. "Other immune cells associated with increased pertussis risk include IgD+ CD38br AC and CD24+ CD27+ %B cells." (PMID 39612418, 2024).
plasma cell leukemia (2 papers, 2022 to 2024). An aggressive plasma cell neoplasm characterized by the presence of neoplastic plasma cells in the peripheral blood. "This increased survival was also observed in plasma cell leukemia where triggering of CD27 with CD70 rescued plasma cells from drug-induced apoptosis via regulation of p38 and ERK 1/2 MAP kinases of the MEK pathway and the downstream transcription factor AP-1." (PMID 34991665, 2022). "This plasma cell leukemia was negative for CD27 and CD138, which is a rare finding and associated with aggressive biological behavior." (PMID 39202633, 2024). "The related plasma cell leukemia by way of contrast shows robust CD27 expression." (PMID 34991665, 2022).
respiratory failure (2 papers, 2021). The significant impairment of gas exchange within the lungs resulting in hypoxia, hypercarbia, or both, to the extent that organ tissue perfusion is severely compromised. "Patients requiring respiratory failure showed depressed CD27, CXCL1, CXCL13, Gal-1, Gal-9, HO-1, IL-18, LAMP3, MCP-3, TNFRS12A." (PMID 34608231, 2021).
rheumatic disease (2 papers, 2023 to 2025). "Therefore, our study highlights the investigation of CD4 T cells and their development in early rheumatic disease, potentially using CD27 to identify subsets of interest in comparison to controls." (PMID 37306812, 2023). "Perhaps this CD27+ CD4 subset is linked to a more general state of inflammation in rheumatic diseases, rather than an axSpA-specific process." (PMID 37306812, 2023).
tetanus (2 papers, 2017 to 2022). A serious infectious disorder that follows wound contamination by the Gram-positive bacterium Clostridium tetani. "ACR50, ACR70, DAS, EULAR good response, CD3 + (T cell), CD19 + (B cell) and CD19 + CD27+ (memory B cell) counts, tetanus and pneumococcal antibody levels were secondary end points." (PMID 28724365, 2017).
thymoma (2 papers, 2021 to 2024). A neoplasm arising from the epithelial cells of the thymus. "CD27 was scantly stained in a small proportion of lymphocytes infiltrating the thymoma." (PMID 35145909, 2021). "CD19+IgD+CD27+ non-switched memory B cells assembled around tertiary lymphoid tissue in thymomas, especially in patients with TMG, whereas a few scattered cells were observed in thymoma tissue from the T group." (PMID 38302676, 2024).
thyroiditis (2 papers, 2025). Inflammation of the thyroid gland. "Clinically, patients with ICI-induced thyroiditis were found to have significantly elevated levels of CD27+ CD4+ TEM cells in their PBMCs, compared to those without thyroid involvement." (PMID 40535343, 2025).
ZIKV infection (2 papers, 2020 to 2025). "A study in a mouse ZIKV infection model described a distinct population of TCF1hi CD27+ NK cells, called “NK memory stem cells”, which showed increased antiviral activity compared to their CD27− or naive CD27+ counterparts." (PMID 40498022, 2025). "These cells also demonstrated greater antiviral potential than naïve CD27+ NK cells when adoptively transferred to Zika infected mice." (PMID 33370392, 2020). "Here we show that Zika virus infection induces memory like NK cells that express CD27." (PMID 33370392, 2020). "The enhanced production of IFN-γ by CD27+ NK cells at memory time point prompted us to investigate whether CD27+ memory like NK cells are generated after ZIKV infection and whether such cells play a role in antiviral immunity." (PMID 33370392, 2020).
Achalasia (1 paper, 2023). A disorder of esophageal motility characterized by the inability of the lower esophageal sphincter to relax during swallowing and by inadequate or lacking peristalsis in the lower half of the body of the esophagus. "We found the proportions of circulating lymphocytes were similar between achalasia and controls except for the increased populations of GNLY+ CD8+ T cells (Tc8), CD27+ B cells (B2), and plasma in achalasia." (PMID 37542039, 2023). "Next, achalasia-associated transcriptional changes of lymphocytes in peripheral blood were analyzed, especially for GNLY+ CD8+ T cells, CD27+ B cells, and plasma, which were proportionally increased in achalasia." (PMID 37542039, 2023).
acute lymphoblastic leukemia (1 paper, 2022). Leukemia with an acute onset, characterized by the presence of lymphoblasts in the bone marrow and the peripheral blood. "Co-expression of CD70 and CD27 is also present on AML and B cell acute lymphoblastic leukemia (B-ALL) blasts, on malignant B cells of chronic lymphocytic leukemia (B-CLL) and subtypes including hairy cell leukemia and its prolymphocytic variant." (PMID 34991665, 2022).
adenoma (1 paper, 2024). A neoplasm arising from the epithelium. "Furthermore, the percentage of antibody-secreting CD19+CD38+CD27+ plasma cells also decreased in the adenoma grade II group (2.775 vs. 0.405, P < 0.0001), adenoma grade III group (2.775 vs. 1.230, P = 0.0015), and CRC group (2.775 vs. 1.280, P = 0.0155) compared with that in the control group." (PMID 38343544, 2024).
anaemia (1 paper, 2016). "Collectively, treatment significantly reduced inflammation and anaemia, accompanied by increasing the numbers of IgG+ IgD− CD27+ CD19+ memory B cells and decreasing the numbers of plasmablasts in UC patients." (PMID 26800315, 2016).
appendicitis (1 paper, 2023). Acute inflammation of the vermiform appendix. "T cells in complex appendicitis displayed an increased differentiated phenotype compared to simple appendicitis, including a loss of both CD27 and CD28 by CD4+ T cells and to a lesser extent by CD8+ T cells." (PMID 38239362, 2023). "This augmented pro-inflammatory activity of CD4+ T cells in complex appendicitis is in line with the reduced expression of CD27 and CD28 indicating an increased effector phenotype of CD4+ T cells in the appendix of children with complex compared to simple appendicitis." (PMID 38239362, 2023).
autoimmune lymphoproliferative syndrome (1 paper, 2021). Autoimmune lymphoproliferative syndrome (ALPS) is a rare, inherited disorder characterized by non-malignant lymphoproliferation, multilineage cytopenias, and a lifelong increased risk of Hodgkin's and non-Hodgkin's lymphoma. "The authors found that a minority of patients, particularly those affected by CD27 deficiency, Di George syndrome, WHIM syndrome or autoimmune lymphoproliferative syndrome (ALPS), develop T cell LPDs." (PMID 33918597, 2021).
autoimmune myocarditis (1 paper, 2023). Autoimmune myocarditis is an autoimmune disease that affects the heart. "In an in-vivo experimental autoimmune myocarditis (EAM) model, activated cardiac NK cells expressed CD27 and depletion of CD27+ NK cells during EAM resulted in increased disease severity, including elevated fibrosis and an influx of cardiac infiltrating eosinophils." (PMID 37465675, 2023).
Autosomal dominant hyper-IgE syndrome (1 paper, 2021). 2000 IU/ml), recurring staphylococcal skin abscesses, and recurrent pneumonia with formation of pneumatoceles. "Autosomal dominant hyper-IgE syndrome patients were previously reported to have significantly decreased CD27+ memory B cells, including both CD27+IgD− class-switched memory B cells and CD27+IgD+ non-class-switched memory B cells." (PMID 34805040, 2021).
basal cell carcinoma (1 paper, 2019). A carcinoma involving the basal cells. "IPA analysis of DEGs revealed that PCP pathway was the top canonical pathways along with HMGB1 signaling, eicosanoid signaling, basal cell carcinoma signaling, CD27 signaling in lymphocytes following exposure to both doses of fipronil with or without LPS." (PMID 30709343, 2019).
biliary tract cancer (1 paper, 2024). "Conversely, the expression of CD24 on CD25+ CD24+ CD27+ B cells is positively correlated with biliary tract cancer, confirming CD24 as a risk factor and BAFF-R (B-cell activating factor receptor) as a protective factor.BAFF-R is a surface receptor found on B cells that specifically binds to BAFF." (PMID 39050844, 2024). "Similarly, the risk estimation for biliary tract cancer by CD25 on CD24+ CD27+ was 1.04, CD25 on CD24+ CD27+ showed a significant association with biliary tract cancer risk (OR=1.04, 95% CI=1.01–1.08, P=0.0074)." (PMID 39050844, 2024). "Within the phenotype of immune cells expressing CD20 on CD20- CD38-, B cells exert a protective effect against biliary tract cancer risk, whereas cells lacking CD20 expression such as CD20- AC and CD27 on CD20- CD38- promote the risk of biliary tract cancer." (PMID 39050844, 2024).
brain tumors (1 paper, 2022). "Increased CD27 expression could be found in several human B cell malignancies and elevated levels of soluble CD27 were detected in CSF of PCNSLs compared to other brain tumors." (PMID 36153593, 2022).
Chagas cardiomyopathy (1 paper, 2014). A disease of the cardiac muscle developed subsequent to the initial protozoan infection by trypanosoma cruzi. "Elevated levels of serum soluble CD27 were observed in infected individuals with Chagas cardiomyopathy, indicating its potentiality as an immunological marker for disease progression in endemic areas." (PMID 25111833, 2014).
chronic renal failure (1 paper, 2025). "Furthermore, studies in children with chronic renal failure have demonstrated a reduced population of CD5+ innate B cells and CD27+ memory B cells." (PMID 40276114, 2025).
cognitive decline (1 paper, 2025). "Within the B cell compartment, IgD− CD27− %lymphocyte appeared to be potentially neuroprotective, whereas CD27+ memory B cells and CD38+ transitional B cells were identified as possible risk factors for cognitive decline." (PMID 40931570, 2025). "Conversely, CD27 expression on memory B cells and CD38 on transitional B cells demonstrated associations with cognitive decline." (PMID 40931570, 2025).
cryoglobulinemia (1 paper, 2015). Cryoglobulinemia is a type of vasculitis that is caused by abnormal proteins (antibodies) in the blood called 'cryoglobulins.' At cold temperatures, these proteins become solid or gel-like, which can block blood vessels and cause a variety of health problems. "In HCV infection with cryoglobulinemia, CD21lo CD27+ B cells have decreased mobilization of calcium after BCR stimulation." (PMID 26649443, 2015). "The marginal zone like IgM+ CD21lo CD27+ B cells in HCV infected patients with cryoglobulinemia show reduced calcium flux in response to BCR stimulation." (PMID 26649443, 2015). "In HCV infected patients with cryoglobulinemia, marginal zone like B cells that are IgM+ CD21lo CD27+ are enhanced in the periphery." (PMID 26649443, 2015). "Decreased BCR signaling has also been observed in CD21+ CD27+ B cells of HCV donors with cryoglobulinemia." (PMID 26649443, 2015).
cryptococcosis (1 paper, 2020). An acute or chronic, localized or disseminated infection by Cryptococcus neoformans. "Most striking was the prominent high frequency of PD-1 on circulating CD27+ activated memory, tissue-like memory, and plasmablasts/plasma cells in healthy controls and in the cryptococcosis coinfected group." (PMID 31871098, 2020).
cystic teratoma (1 paper, 2018). "More detailed B cell analysis from the aspirate of a cystic teratoma confirmed presence of IgM, IgG, and IgD expressing CD19+ cells, in addition to less frequent CD27++CD38++ ASCs." (PMID 29406578, 2018).
delirium (1 paper, 2024). A disorder characterized by confusion; inattentiveness; disorientation; illusions; hallucinations; agitation; and in some instances autonomic nervous system overactivity. "We found that among the numerous B cell subsets, both unswitched memory B cells and CD27 on memory B cells were causally associated with delirium." (PMID 38379709, 2024). "We then further investigated the causal associations between various subsets of B cells during maturation and delirium and found that unswitched memory B cells and CD27 on memory B cells may be associated with the development of delirium." (PMID 38379709, 2024). "In addition, based on the exploration of markers during B cell subsets development, we found that CD27, as a memory B cell signature marker, was likewise significantly associated with delirium (β = 0.039, p = 0.031)." (PMID 38379709, 2024). "The results of the annotation of the screened SNPs suggest that CD27 and CD40 may be key molecules mediating the involvement of B cells in delirium risk." (PMID 38379709, 2024).
diabetic retinopathy (1 paper, 2025). "Together, these findings suggest that the protective effect of LAT2 against DR may be partly mediated by CD27+ switched memory B cells, highlighting the importance of adaptive immune pathways in the pathophysiology of diabetic retinopathy." (PMID 40747309, 2025).
dysplasia (1 paper, 2020). A usually neoplastic transformation of the cell, associated with altered architectural tissue patterns. "When comparing other groups, CD40, TIM-3, and CD27 also significantly discriminated ICC group from dysplasia and Ctrl HPV+ groups (AUC ranging from 0.82 to 0.91)." (PMID 32802959, 2020).
generalized anxiety disorder (1 paper, 2023). An anxiety disorder characterized by excessive and difficult-to-control worry about a number of life situations. "By FDR correction (PFDR<0.05), we found two immunophenotypes to be protective against generalized anxiety disorder: CD24+CD27+B cells and CD28+CD4+T cells." (PMID 38264647, 2023).
graft versus host disease (1 paper, 2023). An immune system disorder that occurs after allogeneic hematopoietic stem cell transplant and is a reaction of donor immune cells against host tissues. "TSCM cells, featured by CD45RA+ CD45RO− CD27+ CD28+ CCR7+ CD62L+ CD95+ CD122+ CD127+, were first discovered in mouse models of human graft versus host disease (GVHD) in 2005 and isolated in vitro in 2013." (PMID 38049832, 2023).
HCMV infection (1 paper, 2022). "Considering the time course of infection, the expression of CD27 and CD28 was progressively lost after HCMV infection to reach a stable CD27-/CD28-, CCR7-, CD45RA+, CD8+ TEMRA phenotype during chronic infection such as in HV hosts with a latent HCMV infection." (PMID 36532017, 2022).
helminth infection (1 paper, 2014). "Blinded to helminth infection status, T cell differentiation (CD45RO, CD27), activation (HLA-DR, CD38) and CCR5 expression was determined at baseline and 3 months after Albendazole/Praziquantel treatment." (PMID 24675895, 2014). "Independent of helminth infection status, CD38 expression alone was a characteristic of “naïve” CD27−/CD45RO− CD4 and CD8 T cells, whereas co-expression with HLA-DR was exclusively detected on memory T cells." (PMID 24675895, 2014).
hemorrhoid (1 paper, 2024). Dilated veins in the anal canal. "In addition, although MR results showed that UC could also increase the incidence of hemorrhoids, it was considered that most IBD-related susceptibility gene loci were simultaneously associated with UC and CD27." (PMID 39030236, 2024).
hyperglycaemia (1 paper, 2015). "However, the relative contribution of hyperglycemia to increasing CD27- MAIT cells proportions seems to show a stronger relationship between older diabetics, rather than younger." (PMID 25625430, 2015). "In order to evaluate the contribution of hyperglycaemia to alterations among CD27- MAIT cells, we tested to see if CD27- MAIT cell proportional differences correlated with HbA1c." (PMID 25625430, 2015). "Since we observed a significant correlation between increasing CD27- MAIT cell proportions and increasing HbA1c levels, we cannot exclude the possibility that changes we observed in this compartment are related to hyperglycemia." (PMID 25625430, 2015). "These intriguing results suggest that although hyperglycaemia may contribute to increased proportions of CD27- MAIT cells among older juveniles, alternate explanations are necessary to fully explain the increased CD27- MAIT cell proportions we observed in T1D<11y.o." (PMID 25625430, 2015).
hypertrophy (1 paper, 2021). Hypertrophy is the increase in the volume of an organ or tissue due to the enlargement of its component cells. "However, some pathways, such as the production of nitric oxide and reactive oxygen species in macrophages, cardiac hypertrophy signaling, CD27 signaling, and IL8 signaling, were enriched LPS + JQ1-treated cells." (PMID 33893325, 2021).
ICF syndrome (1 paper, 2014). "This may lead to the suspicion of several deficiencies, most affecting late stages of B-cell development (e.g., CD27 or CD21 deficiencies), or ICF syndrome." (PMID 25505547, 2014).
IgA deficiency (1 paper, 2020). "Selective IgA deficiency patients are defective in CD27+ and CD27− IgA memory formation." (PMID 32355559, 2020).